CHIT1 (chitinase 1)
Description:
Degrades chitin, chitotriose and chitobiose. May participate in the defense against nematodes and other pathogens. Isoform 3 has no enzymatic activity.
Synonyms: CHIT; CHI3; CHITD
Tractability: Small molecule: a structure with a bound ligand is known; a high-quality ligand is known; it has a high-quality binding pocket. Antibody: its Gene Ontology location is reachable by antibodies, with high confidence; UniProt places it where antibodies can reach, with medium confidence; UniProt predicts a signal peptide or a membrane-spanning region. PROTAC: a small molecule that binds it is known.
Target class: Enzyme; Hydrolase
Gene: Protein-coding gene on chromosome 1 (203,212,827 to 203,273,641, reverse strand). Ensembl gene ENSG00000133063.
Subcellular location: Secreted; Lysosome
Pathways (Reactome):
Digestion and absorption: Digestion of dietary carbohydrate
Immune System: Neutrophil degranulation
Gene Ontology:
Molecular function: chitinase activity; endochitinase activity; protein binding; chitin binding; hydrolase activity, hydrolyzing O-glycosyl compounds
Biological process: chitin catabolic process; immune response; polysaccharide digestion; response to bacterium; carbohydrate metabolic process
Cellular component: extracellular region; specific granule lumen; tertiary granule lumen; lysosome
Genetic constraint (gnomAD): Loss-of-function variants: 47 observed, 52.24 expected, observed/expected ratio (o/e) 0.9, 90% interval 0.71 to 1.15. The upper end of that interval is the gene's LOEUF score, 1.15, which puts it in group 5 of 6, group 1 being the genes least tolerant of losing a copy. Missense variants: 552 observed, 591.56 expected, observed/expected ratio (o/e) 0.93, 90% interval 0.87 to 1. Synonymous variants: 236 observed, 235.84 expected, observed/expected ratio (o/e) 1, 90% interval 0.9 to 1.12.
Homologues: Orthologues: chimpanzee CHIT1 (99% identical), macaque CHIT1 (94% identical), pig CHIT1 (80% identical), rabbit CHIT1 (78% identical), rat Chit1 (76% identical), mouse Chit1 (75% identical), guinea pig CHIT1 (61% identical), Drosophila melanogaster Cht7 (49% identical), zebrafish chia.1 (45% identical), Drosophila melanogaster Cht10 (41% identical), Caenorhabditis elegans cht-1 (40% identical), Drosophila melanogaster Cht8 (39% identical), and 37 more. Paralogues in human: CHIA (52% identical), CHI3L1 (44% identical), CHI3L2 (44% identical), OVGP1 (41% identical), CTBS (17% identical), CHID1 (15% identical).
Diseases named in the same sentence as CHIT1 in open-access papers:
CHIT1 is named in the same sentence as 120 diseases in open-access papers, as found by Europe PMC text mining. Sharing a sentence is not in itself a finding about the gene and the disease. The quoted sentences say what the papers report.
pulmonary fibrosis (19 papers, 2014 to 2025). Chronic progressive interstitial lung disorder characterized by the replacement of the lung tissue by connective tissue, leading to progressive dyspnea, respiratory failure, or right heart failure. "TGF-β is a potent profibrotic cytokine that mediates pulmonary fibrosis especially associated with profibrotic activity of CHIT1." (PMID 35370755, 2022). "In the lung, CHIT1 is expressed in a distinct subgroup of profibrotic macrophages and has been shown to play a central role in pulmonary fibrosis." (PMID 40928208, 2025). "Conversely Chit1 is highly expressed in the human lung but has also been shown to be important in the development of bleomycin-induced lung fibrosis and is upregulated in human idiopathic pulmonary fibrosis." (PMID 40996619, 2025). "One of the immunological effects induced by CHIT1 is pulmonary fibrosis through increased TGF-β signaling." (PMID 38137331, 2023). "Preclinical studies using animal model of pulmonary fibrosis further demonstrated that both CHIT1 and CHI3L1 are sufficient and required for fibroproliferative responses." (PMID 35370755, 2022). "In summary, recent studies strongly support an important role of CHIT1 in the pathogenesis of pulmonary fibrosis via modulation of TGF-β1 signaling and effector function." (PMID 35370755, 2022). "Recently, increasing number of studies are demonstrating that chitinase and chitinase like proteins (C/CLPs) represented by CHIT1 and CHI3L1 are significantly implicated in the pathogenesis of various human diseases including pulmonary fibrosis." (PMID 35370755, 2022). "Here we will overview the recent progress that revealed a new paradigm on the pathogenesis of pulmonary fibrosis and will discuss a new therapeutic strategy by targeting both CHIT1 and CHI3L1." (PMID 35370755, 2022). "Mechanistic studies demonstrated that CHIT1 enhances TGF-β1-stimulated fibrotic cellular and tissue responses and TGF-β1 signaling, which suggests that CHIT1 is a fibrogenic modifier contributing to the pathogenesis of pulmonary fibrosis." (PMID 35222369, 2022). "Lung fibrosis is significantly reduced in CHIT1 knockout mice in a bleomycin-induced lung fibrosis animal model, and it is suggested that this chitinase plays an important role in tissue remodeling and fibrogenesis in the lung." (PMID 34203467, 2021). "Chit1 expression in mice has been shown to be correlated with severity of bleomycin-induced pulmonary fibrosis (with overexpression leading to increased severity and Chit1−/− mice exhibiting reduced pulmonary fibrosis)." (PMID 24786987, 2014). "Notably, previous in vitro studies showed the efficacy of CHIT1 inhibition in a bleomycin‐induced pulmonary fibrosis model." (PMID 40928208, 2025). "CHIT1 was shown to be among the topmost abundantly represented genes of novel profibrotic macrophage populations exclusively present in lungs of patients with lung fibrosis." (PMID 36902148, 2023). "Interestingly, a recent report demonstrated that SPP1high fibrogenic macrophages contribute significantly to lung fibrosis in idiopathic pulmonary fibrosis, and these macrophages express high levels of the CHIT1 gene." (PMID 35052861, 2022). "Moreover, studies demonstrated increased CHIT1 activity levels in serum and/or lung samples of patients with IPF and more recently upregulation of CHIT1 in single-cell transcriptomes of novel subpopulation pulmonary fibrosis-specific macrophages." (PMID 35222369, 2022). "Interestingly, it was shown that inhibition of CHIT1 has more favorable therapeutic effects than nintedanib and comparable therapeutic efficiency to pirfenidone in the bleomycin-induced pulmonary fibrosis model." (PMID 35222369, 2022). "Furthermore, in humans, increased CHIT1 expression has been found in areas of the lung affected by granulomata and fibrosis in tuberculosis, sarcoidosis, idiopathic pulmonary fibrosis, scleroderma, and chronic obstructive lung diseases." (PMID 34954872, 2022).
pulmonary fibrosis (continued). "Interestingly, preclinical studies using CHIT1 inhibitors are underway for the prevention of lung fibrosis and may also be efficacious in preventing the generation of inflammatory TLR2 ligands in situ." (PMID 40098951, 2025). "Article: Lee C-M, He C-H, Park JW, Lee JH, Kamle S, Ma B, Akosman B, Cotez R, Chen E, Zhou Y, Herzog EL, Ryu C, Peng X, Rosas IO, Poli S, Bostwick CF, Choi AM, Elias JA, Lee CG (2019 May 13) Chitinase 1 regulates pulmonary fibrosis by modulating TGF-β/SMAD7 pathway via TGFBRAP1 and FOXO3." (PMID 37037591, 2023). "Furthermore, chitotriosidase was involved in the induction of fibrosis in the murine model of interstitial lung disease as the bleomycin-induced pulmonary fibrosis was significantly reduced in Chit1−/− mice and significantly enhanced in lungs from Chit1 overexpressing transgenic mice." (PMID 26881065, 2016). "Specifically, we want to highlight glycan-regulating proteins linked to macrophages, which hold promise as therapeutic targets in pulmonary fibrosis and sarcoidosis using as examples fucosyltransferases (FUTs), neuraminidase-1 (NEU1), and chitinase-1 (CHIT1)." (PMID 38550597, 2024). "A recent study by our group described significant macrophage-derived activation of CHIT1 in IPF patients and a pulmonary fibrosis animal model." (PMID 36902148, 2023). "The recent findings from single-cell RNA-Seq data from mice and human lung fibrosis revealed the presence of a distinct profibrotic macrophage subtype in the fibrotic lung, with a higher level of CHI3L1, CHIT1, APOE, and integrins." (PMID 36626225, 2023). "In this review, we will discuss specific roles and regulatory mechanisms of CHIT1 and CHI3L1 in profibrotic cell and tissue responses as novel therapeutic targets of pulmonary fibrosis." (PMID 35370755, 2022). "ChIT1 and CHI3L1 distinctly contribute to pulmonary fibrosis using unique receptors or interacting molecules and signaling pathways." (PMID 35370755, 2022). "With these limitations in mind, here the molecular and mechanistic implications of CHIT1 and CHI3L1 as potential therapeutic targets are discussed based on up-to-dated and common lung pathologies of pulmonary fibrosis." (PMID 35370755, 2022). "Dysregulated expression of CHIT1 and CHI3L1 was noted in the patients with pulmonary fibrosis and their levels were inversely correlated with clinical outcome of the patients." (PMID 35370755, 2022). "A substantial body of literatures are strongly support that both CHIT1 and CHI3L1 contribute to the development and progression of pulmonary fibrosis through regulation of profibrotic macrophage activation and/or invasive myofibroblast differentiation." (PMID 35370755, 2022). "Recent studies also demonstrated that CHIT1 is dysregulated in lung diseases characterized by inflammation and remodeling such as bacterial infection, asthma, COPD and pulmonary fibrosis." (PMID 35370755, 2022). "Chitinase 1 (CHIT1) plays a role in the pathogenesis of pulmonary fibrosis by modulating canonical and noncanonical TGF-β signaling via interaction with TGFBRAP1 and FOXO3." (PMID 37037591, 2023). "Notably, dysregulated expression of CHIT1 and CHI3L1 was noted in the patients with pulmonary fibrosis and their levels were inversely correlated with clinical outcome of the patients." (PMID 35370755, 2022). "Taken together, it can be speculated that activated macrophages in patients with IPF are responsible for the upregulation of CHIT1 and YKL-40 which in turn may contribute to the progression of lung fibrosis." (PMID 35222369, 2022). "However, CHIT1 and CHI3L1 also have similar regulatory functions in the development of profibrotic macrophage activation, fibroblasts proliferation and myofibroblasts differentiation, the major hallmarks of pulmonary fibrosis." (PMID 35370755, 2022).
pulmonary fibrosis (continued). "Although the mechanism or the pathways that CHIT1 and CHI3L1 use to regulate pulmonary fibrosis have not been fully understood yet, these studies identify CHIT1 and CHI3L1 as significant modulators of fibroproliferative responses leading to persistent and progressive pulmonary fibrosis." (PMID 35370755, 2022).
Gaucher disease (17 papers, 2012 to 2025). Gaucher disease (GD) is a lysosomal storage disorder encompassing three main forms (types 1, 2 and 3), a fetal form and a variant with cardiac involvement (Gaucher disease - ophthalmoplegia - cardiovascular calcification or Gaucher-like disease). "Chitotriosidase (Chit1) is an enzyme associated with various diseases, including Gaucher disease, chronic obstructive pulmonary disease, Alzheimer disease and cystic fibrosis." (PMID 27716783, 2016). "CHIT-1 is classically associated with lysosomal storage diseases like Gaucher’s disease, due to its increased levels in the patients’ CSF." (PMID 24295388, 2013). "Specifically, elevated Chit1 serum levels are associated with atherosclerosis, COPD, Alzheimer's disease and β-thalassemia, and is a biomarker for Gaucher's disease which affects lysosomal storage." (PMID 33796101, 2021). "Elevations of CHIT1 activity or plasma levels have been reported in patients with elevated inflammatory response, e.g., Gaucher disease, sarcoidosis and Alzheimer’s disease." (PMID 32235817, 2020). "The increased circulating CHIT1 activity is a biomarker of lysosomal storage diseases such as Gaucher’s disease and is used to monitor progression or the efficacy of treatment with enzyme replacement therapy." (PMID 28421328, 2017). "Chit1 is thought to play important roles in pathogenesis of different diseases, such as Gaucher disease, COPD, Alzheimer’s disease and cystic fibrosis." (PMID 27716783, 2016). "Since Chit1 levels are 1000-fold-elevated in the plasma of patients with Gaucher disease, an autosomal recessive lysosomal storage disorder, it was the first mammalian chitinase to be cloned and purified." (PMID 27716783, 2016). "The Chit1 level is elevated in Gaucher disease, in smokers and in patients with COPD and Alzheimer disease." (PMID 25941933, 2015). "The level of Chit1 is elevated in Gaucher disease, in smokers and in patients with chronic obstructive pulmonary disease (COPD) and Alzheimer disease." (PMID 25294623, 2014). "Another up-regulated gene of interest is CHIT1 (743 fold, chitinase 1), elevated in Gaucher disease, atherosclerosis and tuberculosis, suggesting unanticipated roles in bone repair." (PMID 23844045, 2013). "The Chit1 level is markedly elevated in the plasma of patients with Gaucher disease, an autosomal recessive lysosomal storage disorder." (PMID 23185612, 2012). "Chit1 is increased in individuals with Gaucher disease, chronic obstructive pulmonary disease (COPD), and Alzheimer’s disease and in smokers." (PMID 23185612, 2012). "Human chitotriosidase (CHIT1) is considered to be such a marker of lysosomal involvement, since elevated levels have been demonstrated in several lysosomal storage diseases, including Gaucher disease, GM1-gangliosidosis and Niemann-Pick disease type A/B/C." (PMID 39891741, 2025). "Chitotriosidase (CHIT1) is markedly increased in Gaucher disease patients." (PMID 30655565, 2019). "Chit1 has attracted considerable attention due to its increased expression in individuals with different pathological conditions such as Gaucher disease, chronic obstructive pulmonary disease (COPD), Alzheimer’s disease, atherothrombosis, diabetes mellitus cystic fibrosis as well as in smokers." (PMID 27716783, 2016). "The use of a chitinase detection assay, which measures the presence of chitinase activity via cleavage of the fluorogenic substrate 4-methylumbelliferyl chitotriosidase, showed that CHIT-1 levels were elevated several hundred-fold in the plasma of patients with Gaucher's disease." (PMID 22187561, 2012). "Therefore, CHIT-1 is now being used as a biomarker for the diagnosis of Gaucher's disease." (PMID 22187561, 2012).
Gaucher disease (continued). "However, a major limitation of using this biomarker is that its activity increases in plasma during various inflammatory processes, and reduced/null activity can be observed due to null alleles in the gene that encodes it (CHIT1); and, this biomarker is also not specific to Gaucher disease." (PMID 38474117, 2024). "More recently, CHIT1 has been described as a prognostic biomarker for early MS, and soluble GPNMB, which is secreted from different cell types through a disintegrin and metalloproteinase 10 sheddase activity, was identified as a further biomarker of Gaucher disease." (PMID 29312322, 2017).
Alzheimer disease (16 papers, 2014 to 2025). A progressive, neurodegenerative disease characterized by loss of function and death of nerve cells in several areas of the brain leading to loss of cognitive function such as memory and language. "Altered levels of CHIT1 in the CSF have been shown as a biomarker for other neurodegenerative disorders, such as Alzheimer’s disease, amyotrophic lateral sclerosis (ALS), and multiple sclerosis." (PMID 36052089, 2022). "Elevated serum CHIT1 activities were also reported in atherosclerosis (both coronary and cerebrovascular), and Alzheimer’s disease." (PMID 28421328, 2017). "Chitotriosidase 1 (CHIT1) is a human endochitinase that is believed to play a role in immune system response and is increased in serum and CSF in various neurodegenerative diseases such as Alzheimer’s disease or ALS as a marker of neuroinflammation." (PMID 37289324, 2023). "Additionally, CHIT1 had a protective role in an Alzheimer’s disease rat model and N9 microglia cells." (PMID 34359293, 2021). "Established markers of Alzheimer’s disease and neurodegeneration, including TREM2, SAA1, CHIT1, CRP and PDGFRB demonstrated strong correlations (r > 0.8) in the comparison with SomaLogic measurements." (PMID 41250190, 2025). "Distinct immune markers were found to differentiate FTD from Alzheimer’s disease (AD) and amyotrophic lateral sclerosis (ALS), with GFAP, SPARC, and SPP1 varying between FTD and AD and IL-15, HERV-K, NOD2, and CHIT1 differing between FTD and ALS." (PMID 40305176, 2025). "It is worth commenting that the function of CHIT-1 in the human nervous system has still not been established, with CHIT-1 also being implicated in other neurodegenerative diseases, such as Alzheimer’s disease and multiple sclerosis." (PMID 33815058, 2021).